HES4 (hes family bHLH transcription factor 4)
Description:
Transcriptional repressor. Binds DNA on N-box motifs: 5'-CACNAG-3' (By similarity).
Synonyms: bHLHb42
Tractability: PROTAC: ubiquitination databases record sites on it.
Gene: Protein-coding gene on chromosome 1 (998,962 to 1,000,172, reverse strand). Ensembl gene ENSG00000188290.
Subcellular location: Nucleus
Subcellular location (Human Protein Atlas): Nucleoplasm; Cytosol; Vesicles
Gene Ontology:
Molecular function: protein binding; DNA-binding transcription factor activity, RNA polymerase II-specific; RNA polymerase II cis-regulatory region sequence-specific DNA binding; DNA binding; protein dimerization activity
Biological process: anterior/posterior pattern specification; negative regulation of transcription by RNA polymerase II; regulation of DNA-templated transcription
Cellular component: chromatin; nucleus
Genetic constraint (gnomAD): Loss-of-function variants: 17 observed, 10.47 expected, observed/expected ratio (o/e) 1.62, 90% interval 1.07 to 1.95. The synonymous counts are far from expectation, so gnomAD's model fits this gene poorly and the ratio says little. Missense variants: 297 observed, 196.49 expected, observed/expected ratio (o/e) 1.51, 90% interval 1.37 to 1.66. Synonymous variants: 141 observed, 86.35 expected, observed/expected ratio (o/e) 1.63, 90% interval 1.42 to 1.87.
Homologues: Orthologues: chimpanzee HES4 (99% identical), macaque HES4 (96% identical), dog HES4 (84% identical), pig HES4 (82% identical), tropical clawed frog hes4 (61% identical), zebrafish her9 (61% identical), Drosophila melanogaster E(spl)mbeta-HLH (27% identical), Drosophila melanogaster E(spl)m7-HLH (26% identical), Drosophila melanogaster E(spl)mgamma-HLH (24% identical), Drosophila melanogaster E(spl)mdelta-HLH (22% identical), Drosophila melanogaster E(spl)m3-HLH (21% identical), Drosophila melanogaster E(spl)m8-HLH (20% identical), and 2 more. Paralogues in human: HES1 (59% identical), HES2 (33% identical), HEY1 (29% identical), HEYL (29% identical), HEY2 (28% identical), BHLHE40 (27% identical), HES7 (25% identical), BHLHE41 (24% identical), HES5 (24% identical), HES3 (24% identical), HES6 (24% identical), HELT (21% identical).
Diseases named in the same sentence as HES4 in open-access papers:
HES4 is named in the same sentence as 30 diseases in open-access papers, as found by Europe PMC text mining. Sharing a sentence is not in itself a finding about the gene and the disease. The quoted sentences say what the papers report.
breast carcinoma (5 papers, 2014 to 2024). "High expression of the HES4 gene was also reported to be significantly correlated with activating mutations to Notch genes in breast cancers, which resulted in poorer prognosis." (PMID 38370367, 2024). "Similarly, expression of the HES4 Notch gene is known to be significantly correlated with the presence of activating mutations in multiple breast cancer cell lines, and is associated with poor patient outcomes." (PMID 28912426, 2017). "As a downstream target gene of Notch signaling, HES4 has been reported to act as a prognostic biomarker for various tumors, such as breast cancer and osteosarcoma." (PMID 36672336, 2023). "In this subset of genes, we confirmed three genes with established roles in breast cancer, including HES4, CCND1, IGFBP3, with quantitative RT-PCR analyses." (PMID 31462705, 2020). "Several of these genes have previously been associated with stem cell functions: MAFB and ZNF589 have been shown to be important in lineage-specific haematopoiesis, while HES4 is a down-stream target of the Notch signalling pathway which has been shown to affect breast cancer stem cell activity." (PMID 24583601, 2014).
osteosarcoma (4 papers, 2021 to 2024). A usually aggressive malignant bone-forming mesenchymal neoplasm, predominantly affecting adolescents and young adults. "Previous studies have shown that increased HES4 expression is associated with poor prognosis in acute‒chronic liver failure (ACLF) and osteosarcoma (OS) patients." (PMID 39616302, 2024).
colorectal cancer (3 papers, 2023 to 2024). A primary or metastatic malignant neoplasm that affects the colon or rectum. "BEST4 relays the HES4 signal and downregulates TWIST1 expression to counteract epithelial-to-mesenchymal transition (EMT) induction in colorectal cancer (CRC)." (PMID 39699952, 2024).
Huntington disease (2 papers, 2019 to 2022). Huntington disease (HD) is a rare neurodegenerative disorder of the central nervous system characterized by unwanted choreatic movements, behavioral and psychiatric disturbances and dementia. "Epigenetic dysregulation of HES4 may be closely associated with the development of Huntington’s disease in the nervous system." (PMID 35592698, 2022).
adenoma (1 paper, 2024). A neoplasm arising from the epithelium. "Among the HES family, which is associated with intestinal progenitor cells in adenoma transformation, HES1 and HES4 are a paralog pair, with other members more distantly related." (PMID 39699952, 2024).
Alzheimer disease (1 paper, 2022). A progressive, neurodegenerative disease characterized by loss of function and death of nerve cells in several areas of the brain leading to loss of cognitive function such as memory and language. "The expression of transcription factors in each module had a substantial positive connection, and FOSL1, HES4, and MAFB identified the genes in the M4 module as a possible cluster of transcriptional regulators linked to the start of Alzheimer’s disease." (PMID 35592698, 2022).
B-cell acute lymphoblastic leukemia (1 paper, 2016). A neoplasm of lymphoblasts committed to the B-cell lineage, typically composed of small to medium-sized blast cells. "In human B cells, HES4 inhibits early differentiation and acts as a tumor suppressor with epigenetic silencing in B cell acute lymphoblastic leukemia." (PMID 27782828, 2016).
brain tumors (1 paper, 2016). "Notably, our analysis constitutes the first report on HES4 interaction in human brain tumors." (PMID 27782828, 2016).
calcific aortic valve disease (1 paper, 2023). "HES4 is an important downstream target of Notch signalling and has been identified as being differentially expressed in VIC from calcific aortic valve disease." (PMID 38011284, 2023).
colitis (1 paper, 2020). Inflammation of the colon. "The top 3 predicted upstream regulators in inactive extensive colitis were miR-155-5p, SOCS1, and TREM1, regulating CXCL2 and SOCS1; CXCL2 and SOCS1; and CXCL2, HES4, and TIFA, respectively." (PMID 32731480, 2020).
glioma (1 paper, 2021). A benign or malignant brain and spinal cord tumor that arises from glial cells (astrocytes, oligodendrocytes, ependymal cells). "Methylations of HES4 (FDR = 0.017) and NOV (FDR = 3.26E-3) were each significantly associated with later-onset gliomas, while TCF7 methylation was suggestively associated (FDR = 0.132)." (PMID 34788626, 2021). "HES4-methylated IDHwt (FDR = 9.58E-3) and NOV-methylated IDHwt (FDR = 0.010) gliomas were both significantly enriched in the later-onset cohort, along with HES4-methylated IDHmut-codel (FDR = 0.015) and TCF7-methylated IDHmut-codel (FDR = 0.016) gliomas." (PMID 34788626, 2021).
leukemia (1 paper, 2013). A malignant (clonal) hematologic disorder, involving hematopoietic stem cells and characterized by the presence of primitive or atypical myeloid or lymphoid cells in the bone marrow and the blood. "Notch3, JAG1, Hes2, Hes4 and Hes5 were frequently hypermethylated in B leukemia cell lines and primary B-ALL, in contrast to T-ALL cell lines and patient samples." (PMID 23637910, 2013). "JAG1, Hes2 and Hes4 were commonly methylated in various leukemia cell lines and primary B-ALL and T-ALL but not in normal CD19+ B cells." (PMID 23637910, 2013). "In general, expression of Hes5, Hes4 and Notch3 was restored in methylated leukemia cell lines treated by DAC with or without SAHA, a phenomenon associated with gene demethylation." (PMID 23637910, 2013). "Methylation verification revealed that Notch3, Hes5, Hes2, Hes4 and JAG1 genes were frequently hypermethylated in various leukemia cell lines but not in normal controls." (PMID 23637910, 2013). "Notch3, Hes5, Hes2, Hes4 and JAG1 genes were found frequently hypermethylated in various leukemia cell lines but not in normal controls." (PMID 23637910, 2013).
mantle cell lymphoma (1 paper, 2020). Mantle cell lymphoma is a rare form of malignant non-Hodgkin lymphoma affecting B lymphocytes in the lymph nodes in a region called the ``mantle zone''. "Only a few genes, such as HES4, HEY1, MYC, NOTCH3, NRARP, and TFRC, are similarly regulated in mutationally activated NOTCH1-driven cancers, such as T-cell acute lymphoblastic leukemia (T-ALL), mantle cell lymphoma (MCL), and breast cancer." (PMID 33003595, 2020).
schizophrenia (1 paper, 2025). A major psychotic disorder characterized by abnormalities in the perception or expression of reality. "For instance, HES4 was consistently down-regulated in gene expression and chromatin accessibility in excitatory neurons’ layers 4 to 6, cluster 1, previously associated with abnormal psychomotor behavior in schizophrenia." (PMID 40053590, 2025).
systemic lupus erythematosus (1 paper, 2013). An autoimmune multi-organ disease typically associated with vasculopathy and autoantibody production. "While HES4 was not induced in monocytes treated with IFNα, it was upregulated 7-fold in PBMCs treated with immune complexes that cause inflammation in systemic lupus erythematosus." (PMID 23437063, 2013).
T-cell leukemia (1 paper, 2013). A malignant disease of the T-lymphocytes in the bone marrow, thymus, and/or blood. "Hes5, Notch3 and Hes4 genes were either not expressed or very weakly expressed in highly methylated B leukemia cell lines but were abundantly expressed in unmethylated T cell leukemia cell lines such as T-ALL1 and SupT1." (PMID 23637910, 2013).
uveal melanoma (1 paper, 2022). A melanoma derived from melanocytes of the uveal tract. "It is worth noting that primary uveal melanomas also display significant expression of HES1 and HES4 as well as of HEY1-2 and HEYL." (PMID 35673577, 2022).
tumor (12 papers, 2016 to 2025). "Concurrently, genes promoting tumor growth, including HES4, YBX1, and ARTN, were also upregulated in hmmyCAFs." (PMID 41057994, 2025). "Given the co-expression of BEST4+ and HES4+ in a human colonic epithelial lineage, we sought to investigate their biological interactions during tumour growth." (PMID 39699952, 2024). "Similar results were observed in detecting protein and secreted levels of SPP1, demonstrating that B4GALNT1 could promote the synthesis and secretion of SPP1 from tumor cells via HES4." (PMID 39616302, 2024). "HES4 could both serve as an independent prognostic factor and play a crucial role in tumor progression, molecular interactions, and immune response processes." (PMID 38370367, 2024). "This suggests that HES4 may play a similar role in the SVZ or within tumor cells." (PMID 39935607, 2025). "Therefore, our data identified HES4 as a novel tumor-promoting TF in HCC." (PMID 39616302, 2024). "From a transcriptomic perspective, tumour endothelial cells upregulate angiogenesis-related genes, such as CD99, KLF10, and ADAMTS4, while losing scar tissue-related Notch molecule HES4 and antigen presentation molecule HLA-DRA." (PMID 33532508, 2021). "Although the study did not delve into the potential link between HES4 and tumor cell stemness maintenance, other research suggests its involvement in controlling the proliferative properties of NSCs during retinal development." (PMID 39935607, 2025). "However, in the bulk-seq data of tumor tissues from TCGA-LIHC, MAFG (69.16%) had a greater mediating effect than HES4 (17.08%), possibly because of the higher distribution of MAFG in nonmalignant cells." (PMID 39616302, 2024). "Among them were known cancer/testis antigen genes (PNMA5, SPATA22, ROR1, and CT45A6) and some new candidates (PAX2, HES4, PEG10, NTN4, PDE10A, and POSTN), these genes could be useful tumor markers and potential therapeutic targets." (PMID 30922328, 2019).
cancer (10 papers, 2015 to 2025). A tumor composed of atypical neoplastic, often pleomorphic cells that invade other tissues. "Bioinformatic analysis suggested that HES4 might be associated with the activation of the immune response, bone development, and cancer pathways." (PMID 38370367, 2024). "Elucidating the underlying molecular mechanisms for HES1 and HES4 repression requires the interrogation of the epigenetic information of both TPCS‐like and less malignant cancer cells." (PMID 39731353, 2025). "HES4 is a canonical target gene of Notch1 that plays an important role in normal breast epithelial differentiation and cancer development." (PMID 39545637, 2024). "In both TCGA and GSE121711 datasets, HES4 was up-regulated in cancer samples (TCGA: P < 0.01; GSE121711: P < 0.05)." (PMID 38370367, 2024). "Other Notch targets (HEY1, HEY2 and HES4) also exhibited increased transcript levels in cancer cells compared to benign prostate cells, though the differences in expression were less dramatic than that observed for HES6." (PMID 25864518, 2015). "Little is known about the particular function of HES4 in stem cells and cancer." (PMID 27782828, 2016). "Finally, HES4 was up-regulated in cancer samples in both TCGA-BLCA and GSE121711 datasets." (PMID 38370367, 2024). "In addition, in supratentorial (ST) EPN, NOTCH1 expression was associated with cancer stem cell (CSC) markers, VEGFA and L1CAM, and the ST_EPN_RELA subtype showed the activation of selected key members of the Notch signaling pathway (NOTCH1, JAG1, JAG2, HES4)." (PMID 36293188, 2022). "Consistent with elevated JAG1 in ICC/IDC cancer cells, NOTCH target genes were significantly increased in endothelial cells in clusters 0 (HES1) and 22 (HES1 and HEY1) and SMC (HES4) located the ICC/IDC TME compared to benign prostate." (PMID 36229464, 2022). "Compared with that in normal urothelium cells and other cancer cells, the RNA expression of HES1 and HES4, effectors of Notch signalling, at the single‐cell level is significantly lower in TPCS." (PMID 39731353, 2025).
HES4 also shares sentences with these, for which no sentence is quoted: hepatocellular carcinoma (2 papers); arthrogryposis (1); bladder cancer (1); chronic liver failure (1); COVID-19 (1); infection (1); lymphoma (1); Parkinson disease (1); skeletal disease (1); T-cell acute lymphoblastic leukemia (1); triple-negative breast carcinoma (1).